TACC3 (transforming acidic coiled-coil containing protein 3)
Diseases named in the same sentence as TACC3 in open-access papers (continued):
Sharing a sentence is not in itself a finding about the gene and the disease.
cancer (continued). "Moreover, whole-genome and RNA sequencing detect a recurrent fusion involving fibroblast growth factor receptor and TACC3 fusion (FGFR3-TACC3), which generates an oncogenic protein that promotes tumorigenesis and progression in various cancers." (PMID 28273854, 2017). "Moreover, in several types of tumors, FGFR3–TACC3, a common TACC3 fusion gene, has been proved to promote the growth of cancer cells by promoting cell proliferation." (PMID 29088887, 2017). "The high expression of TACC3 in cancers contributes to the proliferation, metastasis and invasion of tumors and may be a biomarker for cancer prognosis." (PMID 29088887, 2017). "In addition, patients whose tumors had high TACC3 expression exhibited a shortened survival time, and this correlation was more obvious in patients with stage I-II cancers compared with patients with stage III-IV cancers." (PMID 27705912, 2016). "Taken together, these findings indicate that TACC3 may be a potential anti-cancer molecular target either in combination with other drugs or alone." (PMID 27705912, 2016). "Our study demonstrated that TACC3 may be a potential anti-cancer molecular drug target of HDACIs and a potential prognostic indicator for CCA." (PMID 27705912, 2016). "As for the possibility that TACC3 may impact the WHS phenotype in a manner dependent on the dosages of other WHS genes, the identification of an FGFR3-TACC3 fusion protein in human cancer cells has provided some initial insight." (PMID 27777068, 2016). "Aurora-A and TACC3 are frequently overexpressed in human cancers, and it has been proposed that this might contribute to tumourigenesis by reducing the fidelity of spindle assembly, thereby increasing the rate of genetic errors." (PMID 26134678, 2015). "Meanwhile, since TACC3 is actually downregulated in a certain subset of cancers, it remains unclear if TACC3 is a tumor suppressor, an oncogene, or both." (PMID 26682275, 2015). "The expression of TACC3 is altered in different human cancer types." (PMID 25596274, 2015). "It is reported that TACC3 is a promising cancer chemotherapy target and knockdown of TACC3 may efficiently improve the chemosensitivity of cancer cells by modulating a premature senescence program." (PMID 25760075, 2015). "Alternatively, TACC3 may have different functions depending on the type of cell, organ or carcinoma." (PMID 25760075, 2015). "Integration of the recurrent regions identified by WACE and the gene regulatory network analysis uncovered not only many well-known oncogenes like BIRC5and E2F1, but also a number of novel cancer susceptibility genes such as ECT2, TPX2 and TACC3, which are involved in cell cycle and ECM regulation." (PMID 21806811, 2011). "For instance, the Wilcoxon test did not detect a change in expression of cancer-associated genes Tacc3 and Birc5, which had more than 0.2 counts/cell in both groups of neurons, more than 3-fold change in expression, and FDR-adjusted p < 10−5 in the weighted-t-test/χ2-test combination." (PMID 41473326, 2025). "Patients with high PLK4 expression express higher TACC3 mRNA and have drastically worse overall survival, further validating the clinical relevance of TACC3 in cancers with CA." (PMID 36864125, 2023). "Having demonstrated the phenotypic effects of TACC3 inhibition on CC, we next sought to identify the molecular mechanisms of TACC3-mediated CC in cancer cells with CA." (PMID 36864125, 2023). "Here, we uncovered, for the first time, the interphase interactome of TACC3 in the nucleus of cancer cells with CA which we further demonstrated to be crucial for gene transcription and cell cycle progression." (PMID 36864125, 2023). "Therefore, targeting TACC3 for degradation by SNIPERs offers a new option for cancer therapy." (PMID 35589670, 2022). "TACC3, a motor spindle protein, which may be necessary for stabilization of the mitotic spindle, has been proven to be important in the differentiation of various cancer cells." (PMID 33362856, 2020).
cancer (continued). "Interestingly, KIFC1 and TACC3 are also required for acentrosomal spindle assembly in multiple organisms, suggesting that cancer cells may be dependent on these meiotic mechanisms to form bipolar spindles when the centrosome complement of the cell is abnormal." (PMID 31506331, 2019). "In addition, TACC3 overexpression increased the invasive properties of cancer cells." (PMID 29358577, 2018). "Thus, the deregulation of TACC3 undoubtedly perturbs normal physiology and may even contribute to the development of human cancers." (PMID 29358577, 2018). "However, the degree of statistical heterogeneity in TNM stage and lymph node metastasis analysis were large, which may be due to the different types of cancer and cut-off values of TACC3 in the included studies." (PMID 29088887, 2017). "Additionally, a more robust understanding of the upstream regulation of TACC3 is required; this may shed light on the etiology of TACC3 upregulation in various cancers, and provide a starting point for thinking about cancer prevention." (PMID 26682275, 2015). "Interestingly, a number of mutations map to this region in cancer cell lines as well as primary tumours, suggesting that deregulation of Aurora-A and TACC3 interaction might benefit the mitotic fitness of cancer cells." (PMID 26134678, 2015). "Furthermore regulation of ERK and PI3K/AKT by TACC3 may contribute in part to epithelial-mesenchymal transition (EMT) in cancer, a significant contributor to carcinogenesis." (PMID 24550739, 2014). "Since TACC3 is overexpressed in cervical and other cancers and appears to be a key player in EGF/EGFR-driven EMT process, it is possible that depletion of TACC3 may be a good approach to treat cancers that are driven by EGF/EGFR signaling pathways or resistant to anti-EGFR therapy." (PMID 23936413, 2013). "Although the role of TACC3 in human cancer is not clear, mounting evidence suggests that deregulation of TACC3 may be directly or indirectly linked to certain types of human cancer." (PMID 23936413, 2013). "Thus, if TACC3 were a significant player in the pathogenesis of cancer, we would expect that a proportion of these tumors could similarly lose expression of TACC3." (PMID 15918899, 2005). "With the patient’s consent, a cancer gene panel test was performed, which identified FGFR3::TACC3 fusion (F17*; T4) and FGFR3 amplification (copy number = 10)." (PMID 40417325, 2025). "This work showcases the novel application of hydrocarbon-stapled peptides to disrupt the TACC3/CHC protein–protein interaction in a cellular context, highlighting the potential of targeting this interface for future cancer therapies." (PMID 40585227, 2025). "Silencing TACC3 has been suggested to suppress the Wnt/β-catenin and PI3K/AKT signaling pathways, which are known to regulate cancer stem cell-like characteristics." (PMID 39603208, 2025). "Various exon breakpoints of FGFR3-TACC3 have been identified in cancers; these were analyzed to determine the minimum contribution of TACC3 for activation of the FGFR3-TACC3 fusion protein." (PMID 36780330, 2023). "We demonstrated, for the first time, that TACC3 forms distinct functional interactomes regulating different processes in mitosis and interphase to ensure proliferation and survival of cancer cells with CA." (PMID 36864125, 2023). "FGFR is the most common fusion expressed in GBM, specifically fibroblast growth factor receptor 3–transforming acidic coiled coil-containing protein 3 (FGFR3:TACC3), which is the fusion with relevance as a potential target in multiple cancers, including GBM." (PMID 35628161, 2022). "The pooled HRs of increased TACC3 expression on OS in patients with NSCLC, HCC and other cancers respectively were 2.02 (95% CI=1.37-2.96, P=0.000), 2.13 (95% CI=1.40-3.24, P=0.000) and 1.83 (95% CI=1.52-2.22, P=0.000)." (PMID 29088887, 2017).
cancer (continued). "In spite of the emerging link between high TACC3 and impaired DDR, unanswered questions need to be uncovered to have a complete knowledge of TACC3 functionality in human cancer." (PMID 26682275, 2015). "Taken together, these data suggest that TACC3 is enriched in HCC and that TACC3 down-regulation inhibits the proliferation, clonogenicity, and cancer stem cell-like phenotype of HCC cells." (PMID 26219398, 2015). "Cancer cells having high CC scores from the NCI60 panel were shown to be more sensitive to TACC3 inhibitor, BO-264, further suggesting the critical involvement of TACC3 in mediating CC and cell survival." (PMID 36864125, 2023). "However, when we assess the effect of TACC3 inhibitor (KHS101) to FGFR3-TACC3 fusion-transfected cancer cell lines, we need to pay attention to specificity of KHS101 for TACC3." (PMID 29358619, 2018). "Cancer biopsy specimens from 120 patients exhibited TACC3 expression, while those from the remaining 32 were negative for TACC3 expression." (PMID 30341253, 2018). "We note that therapies that inhibit FGFR3 signalling in FT3-positive cancers would not tackle the reduction of TACC3 levels at the mitotic spindle, and mitotic defects will still be present in these cells." (PMID 28855393, 2017). "This function of FT3 is specific to TACC3 as inhibition of FGFR3 signalling does not rescue the TACC3 level on the spindle in these cancer cells." (PMID 28855393, 2017). "The relationships between high TACC3 expression and poor prognoses have been reported in various cancers to date; however, cut-off values for high TACC3 on IHC have not been clarified." (PMID 29135996, 2017). "Silencing TACC3 may suppress the Wnt/β-catenin and PI3K/AKT signaling pathways, which regulate cancer stem cell-like characteristics." (PMID 26219398, 2015). "TACC3 has been identified as an interacting partner of the signal transducer and activator of transcription 5 (STAT5), and its expression has been shown to be correlated with Aurora A expression in certain types of cancers." (PMID 23936413, 2013). "Overall, our findings suggest that TACC3 plays an important role in EGF-mediated EMT and may serve as an attractive therapeutic target for human cancers driven by EGF/EGFR signaling pathways." (PMID 23936413, 2013). "The three human TACC proteins, TACC1, TACC2, and TACC3, are core components of the centrosome and have non-overlapping functions in the normal cell and the cancer cell." (PMID 21113414, 2010). "Additionally, bubble plots of the scRNA-seq data indicated that TACC3 expression is specifically enriched in cancer cells compared with other cell types, suggesting that the biological functions of TACC3 in other cell types are not dominant." (PMID 40866361, 2025). "Furthermore, TACC3 expression significantly correlates with CA20 score in the pan-cancer CCLE dataset, comprising the gene expression profiling of more than 1000 cell lines from 36 different cancer types." (PMID 36864125, 2023). "Although the functions of TACC3 in human cancer are unknown, a TACC3-FGFR3 fusion protein has been detected in a subset of glioblastoma multiforme (GBM) and bladder tumor tissues as well as in various cancer cell lines." (PMID 30341253, 2018). "In addition, this result was further confirmed by IHC staining, which showed strong expression of TACC3 in cancer cells and negative or weak expression in adjacent normal cells from the same patient specimens." (PMID 27248823, 2016). "Since Aurora-A is upregulated in certain cancer cell lines, which could influence the stoichiometry and function of the kinase:co-activator complexes, expression levels of these factors (i.e. Aurora-A, CEP192, TPX2, TACC3 and BORA) were determined across cell lines (Fig. EV1A)." (PMID 39327527, 2024).
cancer (continued). "Moreover, the amount of TACC3–ch-TOG–clathrin at the spindle is limited by the availability of phosphorylated TACC3, and since Aurora-A kinase is amplified or upregulated in a wide range of cancers, it is possible that hyperstabilization of K-fibers occurs in these cells." (PMID 26090906, 2015). "As TACC3 level is higher in actively dividing cells, SNIPER(TACC3) might selectively kill cancer cells that are more actively proliferating than non-tumor cells." (PMID 25375378, 2014).
tumor (99 papers, 2005 to 2025). "High TACC3 levels were associated with reduced overall survival, potentially mediated by immune microenvironment and tumor progression regulation." (PMID 39603208, 2025). "All tumor specimens were removed after 14 days of treatment, and we observed that the tumor progression of the TACC3-deficient group was significantly slower than that of the control group." (PMID 38012214, 2023). "We found that, consistent with previous results, TACC3 deficiency significantly suppressed the tumor growth in vivo." (PMID 38012214, 2023). "Increased TACC3 levels were significantly associated with tumor differentiation (P = 0.004), histological type (P = 0.006), parametrium invasion (P = 0.040), nerve invasion (P = 0.003), surgical margin (P = 0.012), P16 (P < 0.001), and Ki-67 (P = 0.004)." (PMID 34134633, 2021). "In the univariate Cox analysis, age, grade, tumor stage, T classification, M classification, and TACC3 expression were all independent risk factors for OS (p = 2.29e-06, 9.48e-15, 4.67e-20, 1.50e-15, 7.45e-19 and 2.99e-11, respectively)." (PMID 33714201, 2021). "In the present study, we have confirmed that TACC3 is strongly associated with tumor immune infiltration." (PMID 33714201, 2021). "In the present study, we demonstrate that TACC3 is closely associated with tumor immune infiltration and T cell exhaustion in KIRC." (PMID 33714201, 2021). "Increasing evidence shows that overexpression of TACC3 is associated with tumor aggressiveness and poor prognosis in prostate, breast, colorectal, and gastric cancer." (PMID 33714201, 2021). "The results obtained from our TIMER and CIBERSORT analysis demonstrated that there was a significant association between the level of TACC3 expression and the degree of tumor infiltration by B cells, CD8+ T cells, CD4+ T cells and DCs in KIRC tissues." (PMID 33714201, 2021). "SPL interferes with TACC3 function by blocking the TACC3-TOGp complex and causing spindle defects in tumor cells, whereas SNIPER(TACC3) reduces TACC3 protein levels in tumor cells by inducing its polyubiquitylation and proteasomal degradation." (PMID 29135996, 2017). "Higher TACC3 expression was associated with increased mitotic counts, and TACC3 was detected in almost all mitotic tumor cells by IHC." (PMID 29135996, 2017). "Additionally, FGFR3-TACC3 fusion causes mitotic defect by removing endogenous TACC3 from the mitotic spindle, potentially promoting aneuploidy and tumor progression in BC." (PMID 40603902, 2025). "Additionally, high TACC3 expression is linked to an immunosuppressive tumor microenvironment and higher tumor mutational burden, suggesting its involvement in tumor progression and immune evasion." (PMID 40791849, 2025). "In addition, our CIBERSORT analysis also identified a strong association between TACC3 expression and tumor infiltration by follicular helper T cells, Tregs, gamma delta T cells, resting NK cells, resting mast cells and monocytes." (PMID 33714201, 2021). "Higher TACC3 expression was associated with poorer tumor differentiation of FNCLCC in STS." (PMID 29135996, 2017). "All in all, these observations indicate that FOSL1 links KRAS oncogene to genes involved in mitotic fitness, and suggest that AURKA and TACC3 may partially mediate the ‘synthetic sensitivity' of mutant KRAS tumours to FOSL1 loss." (PMID 28220783, 2017). "TACC3 function has been implicated in many different tumour types." (PMID 26134678, 2015). "TACC3 overexpression can facilitate tumor cells in bypassing cell cycle checkpoints by influencing regulatory factors of the cell cycle." (PMID 39603208, 2025). "In murine models, oral administration of DHA significantly attenuated the tumor growth promoted by TACC3 overexpression." (PMID 40866361, 2025). "The effect of TACC3 on the tumor microenvironment was validated via single-cell RNA sequencing in HCC-bearing mouse models." (PMID 40866361, 2025).
tumor (continued). "Our findings provide novel insights into how tumor cells evade immune clearance through lipid metabolic rewiring and suggest that TACC3 is a promising target for enhancing immunotherapy efficacy in HCC." (PMID 40866361, 2025). "In summary, tumor-derived TACC3 impairs the tumor-killing activity of CD8+ T lymphocytes through PUFA metabolism-associated crosstalk." (PMID 40866361, 2025). "As a promoter of epithelial-mesenchymal transition, TACC3 contributes to the acquisition of migratory and invasive properties in cells, thereby promoting tumor progression." (PMID 39603208, 2025). "In vaccine trials, in vivo inhibition of TACC3 triggered immunogenic cell death and enhanced the anti-tumor efficacy of T-DM1 by inducing dendritic cell maturation and increasing cytotoxic T-cell infiltration into the tumor microenvironment." (PMID 40402389, 2025). "Targeting TACC3 disrupts spindle formation, induces cell cycle arrest, blocks mitotic progression, and inhibits tumor cell proliferation." (PMID 39603208, 2025). "Collectively, these findings demonstrate that TACC3 promotes tumor growth and glycolysis, and its oncogenic effects can be partially reversed by glycolysis inhibitors." (PMID 40246827, 2025). "The longer diameter of the orthotopic tumors also demonstrated that ablation of TACC3 more significantly impeded tumor growth in C57BL/6 mice than in nude mice." (PMID 40866361, 2025). "TACC3 expression levels were significantly increased in tumor tissues compared with those in normal tissues in the NSCLC (P < 0.001) and LUAD (P < 0.001) datasets of the TCGA and GEO database." (PMID 39603208, 2025). "In in vivo xenograft assays, TACC3 overexpression significantly enhanced tumor growth, while 2-DG treatment attenuated this effect." (PMID 40246827, 2025). "This study showed a notably high diversity of FGFR3::TACC3 rearrangements in UCs, as was also shown previously for other tumor types." (PMID 39596194, 2024). "The same trend of TACC3 or KIF11 expression level was verified by the Western blotting of collected subcutaneous tumor tissue." (PMID 38012214, 2023). "We performed IHC staining of TACC3 in tumor tissues from 54 patients who received neoadjuvant therapy at our center." (PMID 38012214, 2023). "Pharmacological inhibition of TACC3 or KIF11 can suppress tumor cell proliferation and promote apoptosis." (PMID 38012214, 2023). "In contrast, in pediatric setting and in young adults, the finding of a FGFR3::TACC3 fusion in a tumor displaying pathological features of LGG (whatever the neuroradiological findings) leads to major difficulties in its classification." (PMID 36647073, 2023). "While numerous fusion partners have been described for both FGFR2/3, one of the most common fusion partners with FGFR3 across multiple tumor types is transforming acidic coiled-coil-containing protein 3 (TACC3)." (PMID 37980380, 2023). "To further investigate the prognostic value of TACC3 expression, we collected tumor tissues from 218 patients with PDAC at our center to perform a tissue microarray (TMA)." (PMID 38012214, 2023). "The CIBERSORT was utilized to identify the relative ratios of various TIICs in the TME to assess the link between the expression of TACC3 and tumor immune infiltration in order to establish its effect on the prognosis of LUAD patients." (PMID 35855850, 2022). "Lastly, we investigated the link between TACC3 and tumor-infiltrating immune cells (TIICs) through CIBERSORT and the “Correlation” module of GEPIA." (PMID 35855850, 2022). "Future prospective studies focusing on TACC3 expression and tumor immune milieu will help provide conclusive answers to develop immune-based anticancer therapies." (PMID 35855850, 2022). "TACC3 knockdown improved tumor cell sensitivity to chemotherapeutics through effective regulation of premature senescence." (PMID 34134633, 2021).